USP16 (ubiquitin specific peptidase 16)
Description:
Specifically deubiquitinates 'Lys-120' of histone H2A (H2AK119Ub), a specific tag for epigenetic transcriptional repression, thereby acting as a coactivator. Deubiquitination of histone H2A is a prerequisite for subsequent phosphorylation at 'Ser-11' of histone H3 (H3S10ph), and is required for chromosome segregation when cells enter into mitosis. In resting B- and T-lymphocytes, phosphorylation by AURKB leads to enhance its activity, thereby maintaining transcription in resting lymphocytes. Regulates Hox gene expression via histone H2A deubiquitination. Prefers nucleosomal substrates. Does not deubiquitinate histone H2B. Also deubiquitinates non-histone proteins, such as ribosomal protein RPS27A: deubiquitination of monoubiquitinated RPS27A promotes maturation of the 40S ribosomal subunit. Also mediates deubiquitination of tektin proteins (TEKT1, TEKT2, TEK3, TEKT4 and TEKT5), promoting their stability.
Synonyms: Ubp-M; UBPM
Tractability: PROTAC: UniProt records ubiquitination sites on it; ubiquitination databases record sites on it; its protein half-life has been measured.
Target class: Enzyme; Hydrolase
Chemical probes: SGC-UBD1031 (high quality)
Gene: Protein-coding gene on chromosome 21 (29,024,629 to 29,054,493, forward strand). Ensembl gene ENSG00000156256.
Subcellular location: Nucleus; Cytoplasm
Subcellular location (Human Protein Atlas): Cytosol; Nucleoplasm
Pathways (Reactome):
Metabolism of proteins: Ub-specific processing proteases
Gene Ontology:
Molecular function: cysteine-type deubiquitinase activity; cysteine-type endopeptidase activity; histone binding; histone H2A deubiquitinase activity; ribosomal small subunit binding; transcription coactivator activity; ubiquitin binding; zinc ion binding
Biological process: DNA damage response; monoubiquitinated protein deubiquitination; positive regulation of DNA-templated transcription; positive regulation of ribosome biogenesis; positive regulation of translational elongation; protein homotetramerization; positive regulation of transcription by RNA polymerase II; protein deubiquitination; regulation of transcription by RNA polymerase II; chromatin remodeling; mitotic cell cycle; mitotic nuclear division; regulation of cell cycle; regulation of gene expression
Cellular component: cytoplasm; nucleus; nucleoplasm
Genetic constraint (gnomAD): Loss-of-function variants: 62 observed, 76.16 expected, observed/expected ratio (o/e) 0.81, 90% interval 0.66 to 1.01. The upper end of that interval is the gene's LOEUF score, 1.01, which puts it in group 4 of 6, group 1 being the genes least tolerant of losing a copy. Missense variants: 862 observed, 897.27 expected, observed/expected ratio (o/e) 0.96, 90% interval 0.91 to 1.02. Synonymous variants: 277 observed, 296.23 expected, observed/expected ratio (o/e) 0.94, 90% interval 0.85 to 1.03.
Homologues: Orthologues: chimpanzee USP16 (99% identical), macaque USP16 (98% identical), dog USP16 (92% identical), pig USP16 (91% identical), guinea pig USP16 (87% identical), rat Usp16 (84% identical), mouse Usp16 (83% identical), rabbit USP16 (82% identical), tropical clawed frog usp16 (53% identical), zebrafish usp16 (47% identical). Paralogues in human: USP45 (37% identical), USP19 (20% identical), USP24 (20% identical), USP32 (18% identical), USP9X (18% identical), USP9Y (17% identical), USP15 (17% identical), USP11 (17% identical), USP31 (16% identical), USP38 (16% identical), USP4 (16% identical), USP33 (16% identical), and 59 more.
Diseases named in the same sentence as USP16 in open-access papers:
USP16 is named in the same sentence as 35 diseases in open-access papers, as found by Europe PMC text mining. Sharing a sentence is not in itself a finding about the gene and the disease. The quoted sentences say what the papers report.
Down syndrome (10 papers, 2015 to 2025). "In mice triplication of Usp16 was associated with accelerated senescence, consistent with the early aging phenomena in patients with Down syndrome." (PMID 34136489, 2021). "In this article we also report that trisomy of Usp16 in Down’s Syndrome is linked to a reduction in Wnt pathway activation." (PMID 30504774, 2018). "Thus, USP16 levels may be linked to stem cell defects in the Down syndrome mouse model, although the relevance of this discovery to human Down syndrome is unknown." (PMID 36980227, 2023). "Interestingly, the increased gene dosage of USP16, which is located on human chromosome 21, has been linked to the manifestation of Down’s syndrome, whereas virus-induced downregulation of USP16 has been suggested to be a critical step in tumorigenicity of Hepatitis B virus." (PMID 32129764, 2020). "The function of USP16 in H2A deubiquitination in vivo was demonstrated by RNAi-mediated knockdown, knockout in mice, and overexpression and knockdown in the Down syndrome mouse model and cell lines." (PMID 36980227, 2023). "Similarly, a trisomic imbalance for the USP16 gene, which regulates ubiquitination of H2A-K119 and IKKs, could predispose people with Down syndrome or mosaic Down syndrome to have a “heightened” response to triggers leading to innate immune surveillance and/or senescence." (PMID 34283872, 2021). "Ubiquitin Specific Peptidase 16 (USP16) has been reported to contribute to somatic stem-cell defects in Down syndrome." (PMID 31888715, 2019). "The results provide novel insights into a potential role of dysregulation of USP16 expression in Alzheimer’s dementia in Down Syndrome." (PMID 31888715, 2019). "Taken together, these data support the idea that trisomy of Usp16 plays a role in modulating the Wnt pathway in the context of Down’s syndrome, and that Wnt modulation can improve the defects observed in trisomic mammary gland and fibroblast cells." (PMID 30504774, 2018). "USP16 is upregulated in Down’s syndrome (DS) cells due to extrachromosomal triplication in trisomy 21, downregulation of USP16 partially restores the impaired proliferation in DS somatic stem cells." (PMID 28018215, 2016). "The Usp16 gene is located on human chromosome 21, a chromosome that is triplicated in Down’s syndrome." (PMID 26442100, 2015). "Trisomy of Usp16 was recently associated with reduced HSC self-renewal in a mouse model for Down’s syndrome (Ts65Dn), whose HSCs express 1.5-fold higher levels of Usp16 mRNA than wild type HSCs." (PMID 26442100, 2015). "Consistently, knockout of Usp16 results in mouse embryonic lethality, and overexpression of USP16 in the humanized mouse model of Down syndrome reduces the self-renewal of hematopoietic stem cells and the expansion of mammary epithelial cells, neural progenitors, and fibroblasts." (PMID 36980227, 2023). "In humans, USP16 is on chromosome 21, which is triplicated in Down syndrome." (PMID 36980227, 2023). "USP16 is located on human chromosome 21, which is trisomic in Down syndrome." (PMID 34136489, 2021). "A human Down syndrome cell line with a triplicated USP16 gene had decreased DNA damage response." (PMID 34136489, 2021). "In Down’s Syndrome (DS), triplication of Usp16 dampens the activation of the Wnt pathway." (PMID 30504774, 2018).
prostate carcinoma (7 papers, 2021 to 2024). A carcinoma that arises from epithelial cells of the prostate gland. "USP16 has been identified as a novel regulator of Myc stability, promoting the growth of prostate cancer cells with high tolerance." (PMID 39146353, 2024). "In a study with prostate cancer, USP16 was found to be positively correlated with the c-Myc signature." (PMID 36980227, 2023). "Consistently, the level of USP16 is elevated in human prostate cancer compared to normal prostate tissues." (PMID 36980227, 2023). "Knockdown of USP16 in prostate cancer cell lines reduces cell proliferation and suppresses xenograft tumor growth." (PMID 36980227, 2023). "USP16 depletion in prostate cancer cells reduces cell proliferation, xenograft mass, and colony formation." (PMID 35884607, 2022). "H2A was deubiquitinated by deubiquitinating enzyme USP16, and deubiquitinating of H2A is required for the activation of androgen receptor (AR)-mediated genes in prostate cancers." (PMID 34130705, 2021). "USP16 promote prostate cancer growth in vitro and in vivo by deubiquitinating the oncogene c-Myc." (PMID 35884607, 2022). "A recent study showed that MYC could be regulated by USP16, which further inhibited prostate cancer progression." (PMID 35519620, 2022). "Therefore, the deubiquitination of H2A by USP16 may also play a role in prostate cancer cell proliferation to some extent, which remains further investigated." (PMID 33546726, 2021). "Nuclear USP16 also deubiquitinates PLK1 for mitotic chromosome alignment and c-Myc in prostate cancer." (PMID 36980227, 2023).
hepatocellular carcinoma (5 papers, 2016 to 2023). A malignant tumor that arises from hepatocytes. "Expressions of LINC00161/Linc-USP16 in exosomes derived from hepatocellular carcinoma (HCC) patient serum and HCC cell line supernatants were significantly associated with angiogenesis, metastasis, and poor survival." (PMID 37456253, 2023). "USP16 also deubiquitinates proteins in oncogenic pathways, for example, IGF2BP3 in gallbladder cancer, whereas Ct-HBx inhibits the expression level of USP16 in hepatocellular carcinoma, revealing the intrinsic link to cancer development." (PMID 36980227, 2023). "According to our findings, USP16 methylation is increased in breast metastatic disease, in agreement with findings in hepatocellular carcinoma." (PMID 33918195, 2021). "A recent study reported that USP16 was involved in cancer, and its downregulation promoted hepatocellular carcinoma cells growth." (PMID 31888715, 2019). "USP16 was reported to be involved in hepatocellular carcinoma and decreased expression of USP16 by carboxyl-terminal truncated HBx (Ct-HBx) in live tumor cells promoted stem-like properties." (PMID 31888715, 2019).
autoimmune disease (4 papers, 2020 to 2025). A disorder resulting from loss of function or tissue destruction of an organ or multiple organs, arising from humoral or cellular immune responses of the individual to their own tissue constituents. "As a result, both the maintenance and proliferation of T cells are defective in T cell-specific USP16 knockout mice, and these mice are refractory to T cell-mediated autoimmune diseases including inflammatory bowel disease and EAE." (PMID 32248814, 2020). "Furthermore, USP16 influences T-cell activation and proliferation by regulating calcineurin A activity, reinforcing its role in autoimmune diseases." (PMID 40822862, 2025). "USP16 also functions as a modulator of mature T cell activation, and may, therefore, serve as a new therapeutic target for T cell–mediated autoimmune disease treatment." (PMID 37744384, 2023). "Specific USP16 inhibitors might be of potential efficacy in treating autoimmune diseases mediated by T cells, such as MS." (PMID 32248814, 2020). "Altered DNA methylation of genes, such as, PON1, ADARB2, USP16, UHMK1, and DISC1, was previously reported to be related to cancer or autoimmune diseases." (PMID 37744384, 2023). "Interestingly, increased USP16 levels, a deubiquitinase required for chromosomal segregation in mitosis, were observed in peripheral CD4+ T cells from patients with distinct autoimmune diseases and T cell-specific USP16 knockout mice showed a reduced severity of experimental autoimmune encephalitis." (PMID 34889895, 2021).
gouty arthritis (3 papers, 2023 to 2025). "In the context of gouty arthritis, USP16 contributes to the inflammatory process through drp1-dependent mitochondrial fission and the activation of the NLRP3 inflammasome." (PMID 40822862, 2025). "In conclusion, we found that DUB USP16 induced gouty arthritis via Drp1-dependent mitochondrial fission and NF-κB/NLRP3 signaling." (PMID 37488647, 2023). "Deubiquitinase USP16 induced gouty arthritis via Drp1-dependent mitochondrial fission and NF-κB/NLRP3 signaling." (PMID 37488647, 2023). "Consistently, western blot showed that Drp1 and USP16 were remarkably increased in the joints of mice with gouty arthritis." (PMID 37488647, 2023). "As expected, Drp1 and USP16 were elevated in the synovial tissues from patients with gouty arthritis, compared with control group." (PMID 37488647, 2023). "We thus hypothesized that USP16 might contribute to gouty arthritis via Drp1-dependent mitochondrial fission and NLRP3 inflammasome activation." (PMID 37488647, 2023). "However, the biological function of USP16 in gouty arthritis remains elusive." (PMID 37488647, 2023). "Together, the functional studies indicate that USP16 might act as a key player in gouty arthritis." (PMID 37488647, 2023). "Functional studies further showed that USP16 was highly expressed in MSU-stimulated macrophages and induced gouty arthritis via Drp1-dependent NLRP3 inflammasome activation." (PMID 37488647, 2023). "Studies have shown that the deubiquitinating enzyme USP16 induces gouty arthritis through Drp1-dependent mitochondrial fission and NLRP3 inflammasome activation, with the mechanism being that USP16 mediates Drp1 deubiquitination and stabilization through direct interaction with Drp1." (PMID 41311848, 2025).
colitis (2 papers, 2021 to 2025). Inflammation of the colon. "Importantly, mice with a knockout of USP16 display a reduction in colitis severity, characterized by decreased levels of pro-inflammatory cytokines such as TNF, IL-12, and IL-23." (PMID 40822862, 2025). "Besides, USP16 was observed to be up-regulated in colonic macrophages of IBD patients and the deletion of USP16 in macrophages alleviated DSS-induced colitis and inflammation-associated colon carcinogenesis." (PMID 34956195, 2021).
inflammatory bowel disease (2 papers, 2024 to 2025). A spectrum of small and large bowel inflammatory diseases of unknown etiology. "A study demonstrated that USP16 enhances NF-κB activation by selectively removing K238-linked ubiquitination from IKKβ, thereby promoting p105 phosphorylation and exacerbating inflammatory responses in inflammatory bowel disease (IBD)." (PMID 40822862, 2025). "USP16's regulation is particularly crucial in autoimmune responses and inflammatory diseases, such as inflammatory bowel disease (IBD) and colon cancer, underscoring the diverse mechanistic roles of DUBs in NF‐κB signaling control." (PMID 39678489, 2024).
acute lymphoblastic leukemia (1 paper, 2020). Leukemia with an acute onset, characterized by the presence of lymphoblasts in the bone marrow and the peripheral blood. "However, children with DS are predisposed to acute lymphoblastic leukemia (ALL), indicating that immune cells are possibly regulated by USP16." (PMID 32248814, 2020).
acute monocytic leukemia (1 paper, 2021). Acute monoblastic leukemia (AML-M5), is one of the most common subtypes of acute myeloid leukemia (AML) that is either comprised of more than 80% of monoblasts (AML-M5a) or 30-80% monoblasts with (pro)monocytic differentiation (AML-M5b). "Here we report the creation of a loss of function mutation in the USP16 gene using CRISPR-Cas9 technology in the THP-1 human acute monocytic leukemia (AML) cell line." (PMID 34136489, 2021). "We mutated the USP16 gene in a high differentiation clone of the acute monocytic leukemia cell line THP-1 using the CRISPR-Cas9 system and generated four homozygous knockout clones." (PMID 34136489, 2021).
chronic lymphocytic leukemia (1 paper, 2021). "It has been shown that chronic lymphocytic leukemia cells-derived exosomes can transfer miR-146a to bone marrow-derived mesenchymal stem cells to generate CAFs; this is done by promoting EMT by targeting ubiquitin specific peptidase 16 (USP16)." (PMID 34912797, 2021).
coronary artery disease (1 paper, 2023). "The intrinsic links between USP16 and human cancers, as well as immune response and coronary artery disease, suggest that USP16 can be a potential therapeutic target." (PMID 36980227, 2023).
gallbladder cancer (1 paper, 2023). "Thus, USP16 stabilizes IGF2BP3, which may be the partial mechanism of MNX1-AS1-driven gallbladder cancer." (PMID 36980227, 2023).
glioma (1 paper, 2025). A benign or malignant brain and spinal cord tumor that arises from glial cells (astrocytes, oligodendrocytes, ependymal cells). "Recent research has also identified that lncRNA lncPEAT in gliomas interacts with the ubiquitin-digesting enzyme USP16, suppressing USP16′s recruitment to chromatin and thereby inhibiting the expression of senescence-related genes CDKN1A and CLUSTERIN." (PMID 40149983, 2025).
liver cancer (1 paper, 2016). An epithelial or non-epithelial malignant neoplasm that arises from the liver. "Moreover, the up-regulation of some genes related to the stemness of cancer cells, such as EpCAM, CD133, CD44, Oct4, Nanog, KLF4 and Sox4, in USP16-depleted liver cancer cells also suggests a stemness-suppressing role for USP16." (PMID 27633997, 2016).
lymphocytic leukemia (1 paper, 2022). "It has been shown that lymphocytic leukemia cell exosomes deliver microRNA miR-146a to bone marrow MSCs, where miR-146a mediates the transition of MSCs to TAFs by targeting ubiquitin-specific peptidase 16 (USP16)." (PMID 35741334, 2022).
male infertility (1 paper, 2023). The inability of the male to effect fertilization of an ovum after a specified period of unprotected intercourse. "Some of the functions that USP16 has been linked to include DNA damage repair, immune disease, tumorigenesis, protein synthesis, coronary artery health, and male infertility." (PMID 36980227, 2023).
melanoma (1 paper, 2020). A malignant, usually aggressive tumor composed of atypical, neoplastic melanocytes. "We detected ISG.RS mRNA level in negative control or SOX2 KD melanoma cell lines and observed that SOX2 KD decreased the ISG.RS expression (IDO1, PDL1, IFI27, and USP16)." (PMID 33158915, 2020).
microsporidia infection (1 paper, 2026). "On the other hand, while USP16 levels remained stable, we observed a marked downregulation of both mRNA and protein levels of the BAP1 in response to EnP1 expression and microsporidia infection." (PMID 41499632, 2026).
monocytic leukemia (1 paper, 2022). "In doing so, the authors found that the human monocytic leukemia THP-1 cell line can develop alternative pathways to escape the inactivation mutations of USP16, suggesting that the function of USP16 is potentially redundant, and another unstudied DUB may compensate for the loss of function." (PMID 35625630, 2022).
multiple sclerosis (1 paper, 2019). A progressive autoimmune disorder affecting the central nervous system resulting in demyelination. "In vivo, expression levels of TERC and TERC target genes (TYROBP, TPRG1L and USP16) are upregulated in patients with inflammation-related diseases such as type II diabetes and multiple sclerosis." (PMID 31294790, 2019). "For diabetic patients, TPRG1L and TYROBP were upregulated, whereas TYROBP and USP16 were upregulated in multiple sclerosis patients." (PMID 31294790, 2019).
myeloid malignancies (1 paper, 2021). "In addition, BAP1 and USP16, both of which are H2AK119ub1 DUBs, have antitumor functions and are often absent or mutated in multiple solid tumors and myeloid malignancies." (PMID 34706761, 2021).
Stroke (1 paper, 2025). Sudden impairment of blood flow to a part of the brain due to occlusion or rupture of an artery to the brain. "This discovery suggests that selective USP16/USP4 inhibitors may synergize with existing ROS scavengers to develop novel combinatorial therapeutic strategies for stroke." (PMID 40529211, 2025).